NLGN3 (neuroligin 3)
Diseases named in the same sentence as NLGN3 in open-access papers (continued):
Sharing a sentence is not in itself a finding about the gene and the disease.
ischemia (1 paper, 2023). A hypoperfusion of the BLOOD through an organ or tissue caused by a PATHOLOGIC CONSTRICTION or obstruction of its BLOOD VESSELS, or an absence of BLOOD CIRCULATION. "We here found that Gαi1 and Gαi3 mediated NLGN3-induced Akt activation and neuroprotection against ischemia-reperfusion injury." (PMID 37880221, 2023). "Thus, Gαi1/3-mediating Akt activation is required for NLGN3-induced neuroprotection against ischemia-reperfusion injury." (PMID 37880221, 2023).
leukemia (1 paper, 2025). A malignant (clonal) hematologic disorder, involving hematopoietic stem cells and characterized by the presence of primitive or atypical myeloid or lymphoid cells in the bone marrow and the blood. "We obtained CSF from four patients with DIPG/DMG and four patients with leukemia (negative control group) and performed western blot analysis with antibodies against the N-termini of NLGN3 and CSPG4." (PMID 40791371, 2025).
melanoma (1 paper, 2025). A malignant, usually aggressive tumor composed of atypical, neoplastic melanocytes. "As such, while there are some data supporting functional synapse formation between melanoma cells and neurons, bidirectional electrochemical communication between them, and NLGN3-driven proliferation in melanoma, there is still very little direct evidence." (PMID 41463339, 2025). "The activity-dependent shedding of NLGN3 from the surface of neurons activates the PI3K-mTORC1 signaling pathway in melanoma cells and enhances their proliferative potential." (PMID 41463339, 2025). "NLGN3 is a trophic factor for melanoma cells that is shed from neurons through the action of ADAM10/17." (PMID 41463339, 2025). "RNA-seq and ATAC-seq analyses demonstrate that melanoma cells reactivate enhancer sets that control axon guidance (SLIT2, ROBO1, SEMA3A), neurotransmission (GRIN2A, SYT1, SLC17A7), and synaptic structure (DLG4, NRXN1, NLGN3)." (PMID 41463339, 2025).
neuroblastoma (1 paper, 2021). Neuroblastoma (NB) is the most common solid, extracranial childhood tumor. "The latest research shows that, NLGN3 is up-regulated in neuroblastoma tissues and increases the proliferation through activates the AKT pathway in neuroblastoma cells, which is consistent with our results." (PMID 34485271, 2021).
oligodendroglioma (1 paper, 2018). A well-differentiated (WHO grade II), diffusely infiltrating neuroglial tumor, typically located in the cerebral hemispheres. "Interestingly, two patients with the highest NLGN3 expression had a histological diagnosis of WHO grade III oligodendroglioma, and one can speculate that in these tumors the NLGN3 expression level is relatively high irrespective of the level of NLGN3 that is released by neuronal activity." (PMID 30094719, 2018).
tuberous sclerosis (1 paper, 2025). Hereditary disease characterized by seizures, intellectual disability, developmental delay, and skin and ocular lesions. "Commonly used models are often based on single-gene disorders associated with ASD, such as Tuberous Sclerosis (TSC) and Fragile X syndrome, or high-effect risk genes like SHANK3, NLGN3, and NLGN4, as they offer high construct validity and thereby increase relevance." (PMID 40611277, 2025).
tumor (54 papers, 2017 to 2026). "Neuroligin, a synaptic cell surface protein, mediates trans-synaptic signaling, with NLGN3 being the isoform implicated in the GBM tumor microenvironment." (PMID 38732975, 2024). "The first circuit requires light-induced activation of retinal ganglion cell (RGC) neurons and the release of ADAM10, which cleaves membrane-bound NLGN3 from OPCs to drive tumor initiation." (PMID 41497446, 2025). "Neuronal activity has been shown to directly influence tumor growth through the activity-dependent release of neuroligin-3 (NLGN3), which promotes GBM cell proliferation via activation of the PI3K-mTOR signaling pathway." (PMID 41280918, 2025). "This communication involves the exchange of signals mediated by brain-derived neurotrophic factor (BDNF) and NLGN3 proteins, which contribute to tumor growth and survival." (PMID 38732975, 2024). "For example, the role of NLGN3 in the maturation of excitatory synapses and its broader impact on brain function during tumor intervention needs further investigation." (PMID 39469896, 2024). "Overall, these data indicated that the USP7/KPNB1/YBX1/NLGN3 axis actively regulated tumor progression in GBM." (PMID 38254206, 2024). "The dynamic interplay between the nervous system and tumor growth is elaborated, where neural activity is shown to promote tumor growth through the secretion of growth factors, like NLGN3." (PMID 39202716, 2024). "In this context, the authors showed that tumor growth was dependent on NLGN3 secretion, and that blocking NLGN3 through genetic knockdown or through ADAM10 inhibition results in the arrest of gliomagenesis." (PMID 37511496, 2023). "Given that NLGN3 signaling is responsible for synaptogenesis, this effect is likely due reduced neuron–tumor synaptic activity." (PMID 36614191, 2023). "In paediatric gliomas, the neuronal secretion of neuroligin-3 stimulates tumour growth, and its blockade via the inhibition of the ADAM10 sheddase markedly inhibits tumour growth." (PMID 36230865, 2022). "Nlgn3 exposure also induces feedforward expression of Nlgn3 protein at the transcriptional and translational levels, resulting in further increases in Nlgn3 protein expression in tumor cells." (PMID 34690695, 2021). "Single studies concerning various cancers showed that Pro-NGF/NGF (nerve growth factor), BDNF (brain-derived neurotrophic factor), Ephrin B1, neuroligin-3, pleiotrophin, semaphorin 4F were involved in the regulation of tumor innervation." (PMID 34277455, 2021). "Collectively, these findings identify two potential mechanisms by which activated neurons in the tumor microenvironment can contribute to DIPG invasion through secretion of NLGN3, which warrants further investigation." (PMID 32117746, 2020). "For example, it was recently shown that neuroligin 3, secreted from tumor-promixate neurons, augments tumor growth and creates a positive feedback loop leading to the generation of tumor-derived neuroligin-3." (PMID 30621226, 2019). "We further studied the level of NLGN3 under pathological conditions and analyzed the level of NLGN3 in GBM tissue from patients after tumor resection." (PMID 29777576, 2018). "We examined the relation between NCF (attention and executive functioning, memory, language, visuospatial functioning and psychomotor speed) and neuroligin-3 expression, using multivariable logistic regression models adjusting for tumor grade, location and volume." (PMID 42291752, 2026). "Neuroligin-3 may modulate neuronal and epileptic activity, contributing to both tumor growth and cognitive deficits." (PMID 42291752, 2026). "Importantly, inhibition of the metalloproteinase ADAM10, which cleaves and releases NLGN3, in these models inhibited tumor growth in-vivo." (PMID 41460355, 2025). "ADAM10 inhibition reduces xenograft growth by preventing NLGN3 release into the tumour microenvironment and could represent the basis of new therapeutic strategies." (PMID 38834748, 2024).
tumor (continued). "We could experimentally show that the NLGN3 & ANK2 have tumor-suppressor roles in BRCA as shown by cell viability assay, transwell migration, colony forming and wound healing assay." (PMID 38977697, 2024). "Furthermore, NLGN3 has been shown to phosphorylate key receptors on tumor cells, including VEGF, epidermal growth factor receptor (EGFR), fibroblast growth factor receptor (FGFR), and integrins, thus exerting their biological effects." (PMID 39469896, 2024). "Moreover, elevated NLGN3 transcription mediated by Wnt/β-catenin signaling pathway resulted in increased secretion of NLGN3 into the surrounding tumor microenvironment." (PMID 37443071, 2023). "Venkatesh and colleagues of the Monje lab explained a mechanism of how neuronal activity promotes high-grade gliomal growth, showing that the upregulation of neuroligin-3 (NLGN3) in postsynaptic neurons promotes the proliferation of gliomal tumor cells through the induction of PI3K-mTOR signaling." (PMID 36291792, 2022). "Speculatively, the effects of NLGN3 on both excitatory and inhibitory synapses—and consequently on neural networks—could both promote tumor growth and help preserve cognition." (PMID 35148403, 2022). "In addition, since NLGN3 induced downstream PI3K/Akt signaling, a pathway linked to tumor invasion it is likely that secretion of NLGN3 also contributes to DIPG invasion by activating this pathway." (PMID 32117746, 2020). "Furthermore, authors reported that an increase of the tumour cell proliferation upon treatment with conditioned medium from optogenetically stimulated acute cortical slices was incompletely abrogated following Nlgn-3 knockout." (PMID 32366909, 2020). "Nlgn-3 knockout has thus been observed to significantly reduce tumour growth in vivo." (PMID 32366909, 2020). "Together, these results indicate that not only activity of the tumor region, but also global activity (with and without the tumor included) associates with NLGN3 expression." (PMID 30094719, 2018). "Furthermore, we tested the level of NLGN3 in normal tissues of GBM patients after tumor resection and found that NLGN3 levels are higher in deep brain regions, which is contrary to a normal human brain tissue." (PMID 29777576, 2018). "Together, high levels of NLGN3 in deep brain regions may play a key role in the induction of GBM recurrence after tumor resection." (PMID 29777576, 2018). "Post-hoc analyses showed that patients with moderate NLGN3 expression had significantly higher levels of peritumor (U = 7, P = 0.005), global (U = 2, P < 0.001) and non-tumor (U = 5, P = 0.002) oscillatory brain activity than patients with low NLGN3 expression." (PMID 30094719, 2018). "In addition, recent studies have shown that NLGN3 plays an important role in tumor growth 4,22." (PMID 33754006, 2021). "The tumor suppressor role of the selected genes ANK2 and NLGN3 was elucidated by cell viability assay, transwell migration, colony-forming and wound healing assay in MCF7, MDA-MB-231 and MCF10A cell lines." (PMID 38977697, 2024). "Nevertheless, Venkatesh and colleagues revealed a novel mechanism behind this reciprocal influence, showing that neuron paracrine secretion of neuroligin-3 (NLGN3) facilitates tumor progression and in turn induces a synaptic gene signature in the tumor cell." (PMID 36229714, 2023). "When exposed to soluble forms of the neuronal synaptic protein neuroligin-3 (NLGN3), OPC-like tumor cells proliferated faster." (PMID 35573444, 2022). "GB cells project tumor microtubes (TMs) contact with neurons, and exchange signaling molecules related to Wingless/WNT, JNK, Insulin or Neuroligin-3 pathways." (PMID 35877760, 2022). "The use of ADAM10 inhibitors blocked the release of NLGN3 in the TME and inhibited gliomal growth in vivo, proving that neuronal-activity-regulated secretion is a targetable mechanism against tumor growth." (PMID 36291792, 2022). "In GBM patients NLGN3 levels are high in the deep brain, preparing a pro-GBM tumor microenvironment." (PMID 32265938, 2020).
tumor (continued). "Meanwhile, the Akt pathway, in conjunction with neuroligin-3 (NLGN3) and the phosphoinositide 3-kinase (PI3K)-mammalian target of the rapamycin (mTOR) pathway, exerts profound effects on cell survival and growth regulation within the tumor microenvironment." (PMID 38732975, 2024). "Additionally, neuronal activity can affect the behavior of tumor cells by releasing proteins such as brain‐derived neurotrophic factor (BDNF), NLGN3, and insulin‐like growth factor‐1 (IGF‐1) in the microenvironment." (PMID 39469896, 2024). "Paracrine signaling inhibitors, targeting paracrine factors like NLGN3, IGF‐1, and their downstream signaling pathways could disrupt the supportive TME for tumor cells." (PMID 39469896, 2024). "NLGN3 has been shown to act through the PI3K-Akt-mTOR pathway to induce synaptic gene expression, thus establishing a feed-forward loop in which increased neural activity begets increased tumor sensitivity to this activity." (PMID 36614191, 2023). "Consistent with the lack of tumor formation, Arg1809Cys-mutant neurons do not induce Adam10-mediated cleavage and shedding of Nlgn3, a growth factor required for murine Nf1-OPG initiation and growth." (PMID 35589737, 2022). "Serving as post-synaptic cells, OPC-like tumor cells had increased proliferation with higher activity independent of the soluble NLGN3 mechanism." (PMID 35573444, 2022). "We found, after correcting for tumor volume and location, correlations between the expression level of CD3 or IDH-1 and psychomotor speed; IDH-1, BDNF, ATRX, CK2Beta, GAT-3, NLGN3, SRF, or EAAT1 and memory performance, and P-STAT5b, NLGN3, CK2Beta, or IDH-1 and executive functioning." (PMID 35148403, 2022). "In our data, we found a significant and independent protective effect of NLGN3 on memory and executive functioning, independent of tumor volume and location." (PMID 35148403, 2022). "Therefore, siRNAs targeting NLGN3/ADAM10 are promising for treating glioblastoma by modulating the interaction between neuronal cells and tumor cells." (PMID 34532286, 2021). "In addition, neuronal‒GBM cell interactions have recently emerged as an important factor in tumor growth, as neuronal activity promotes tumor progression by inducing the release of brain-derived neurotrophic factor (BDNF), neuroligin-3, and dopamine." (PMID 34439156, 2021). "NLGN3 could contribute to an interconnected network of DIPG cells and synergy between tumor subclones via the induction of TMs." (PMID 32117746, 2020). "The relation between neuronal activity, NLGN3 expression and tumor progression has not been established in a clinical population of patients with diffuse glioma, which hampers clinical exploitation of these obtained fundamental insights." (PMID 30094719, 2018). "In a follow-up study, the authors used immunodeficient NLGN3 knockout mice bearing xenografts of patient-derived HGG cells to show that, in the absence of NLGN3, tumor growth was almost completely inhibited over a protracted observation period of 6 months (Venkatesh and others 2017)." (PMID 39066464, 2025).
cancer (9 papers, 2018 to 2025). A tumor composed of atypical neoplastic, often pleomorphic cells that invade other tissues. "Activation of the JNK and ERK signaling pathways has demonstrated apoptosis avoidance and regulated cancer cell proliferation, while Akt pathway has been implicated with neuroligin-3 (NLGN3) and the phosphadylinositol-3-kinase (PI3K)-mTOR pathway." (PMID 37686652, 2023). "In this study, we observed overexpression of NLGN3 transformed not only modulated cells themselves, but also other neighbor cells into more cancer stem-like properties." (PMID 37443071, 2023). "Moreover, GBM-derived NLGN3 has an oncogenic function and can induce cancer stem cell (CSC) properties within GBM, which is significant because clinical evidence suggests that an increased number of CSCs may contribute to the failure of conventional therapies." (PMID 38254206, 2024). "Given the marked downregulation of NLGN3 following KPNB1 knockdown, and the previously reported roles of NLGN3 in various cancers, especially in nervous system tumors, we hypothesized that KPNB1 regulated GBM progression through NLGN3." (PMID 38254206, 2024). "NLGN3 and NRXN3 were primarily expressed in cytosolic compartments rather than in the membrane, suggesting that their roles in cancer cells might be different from those in neurons." (PMID 37443071, 2023).
neurodevelopmental disorder (7 papers, 2016 to 2025). A behavioral and cognitive disorder with onset during the developmental period that involves impaired or aberrant development of intellectual, motor, or social functions. "Recently, genes involved in HSCR and ENS development (such as CHD8 and NLGN3) were also found to be implicated in neurodevelopmental disorders indicating that genetic neurodevelopmental processes might be conserved between the CNS and ENS." (PMID 33151932, 2020).
infection (1 paper, 2018). The state of being infected such as from the introduction of a foreign agent such as serum, vaccine, antigenic substance or organism. "Conversely, infection of HT22 cells with shRNA against mouse β-catenin for 48 h significantly decreased endogenous Nlgn3 expression (up to 35%)." (PMID 29503438, 2018).
NLGN3 also shares sentences with these, for which no sentence is quoted: neurological disorders (3 papers); obsessive-compulsive disorder (2); temporal lobe epilepsy (2); Alzheimer disease (1); Angelman syndrome (1); astrocytoma (1); Ataxia (1); Brain atrophy (1); Cognition Deficits (1); cyst (1); depression (1); developmental delay (1); diffuse intrinsic pontine glioma (1); Dravet syndrome (1); hypogonadotropic hypogonadism (1); low grade glioma (1); nervous system tumors (1); Phelan-McDermid syndrome (1); Prader-Willi syndrome (1); psychosis (1); retinoblastoma (1); Tourette syndrome (1); velocardiofacial syndrome (1).